IL6 (interleukin 6)
Diseases named in the same sentence as IL6 in open-access papers (continued):
Sharing a sentence is not in itself a finding about the gene and the disease.
tumor (continued). "A doxorubicin-containing chemotherapy induces IL-6 release in non-tumor bearing mice and is associated with loss of lean body mass, comparable to other IL-6 tumor models." (PMID 34899373, 2021). "Additional effects of IL-6 include attenuation of Th1 responses in the tumor microenvironment, activation of cancer-associated fibroblasts, reductions in CD8 + cytotoxic T lymphocyte populations, increases in immunosuppressive FOXP3 + regulatory T cell populations, and enhanced generation of MDSCs." (PMID 34307378, 2021). "The release of IL-6 from tumor cells may modulate the activity of the inflammation and immunity cells in the tumor microenvironment." (PMID 34576335, 2021). "We previously demonstrated that cytokines like G-CSF and interleukin (IL)-6 in the tumor environment could modulate neutrophil function and enable them to promote tumor growth and angiogenesis." (PMID 34458135, 2021). "IL-6 has been shown to promote tumor proliferation, metastases and symptoms of cachexia." (PMID 32621022, 2021). "In summary, IL-6 may represent a key initiation event for the formation of PGCCs and creation of favorable tumor microenvironment in response to paclitaxel-mediated chemotherapy." (PMID 34588424, 2021). "Indeed, IL-6 secreted by tumor cells promotes the activation of the JAK–STAT signaling pathway, leading to suppression of protein synthesis and muscle wasting." (PMID 34203023, 2021). "Notably, high levels of tumor IL-6R and serum IL-6 expression are strongly correlated with poor survival of patients with HNSCC." (PMID 34689150, 2021). "Moreover, the outcomes of this study displayed a decrease in the density of IL-6 and IL-8 through knockdown of Beclin-1 and a reduction in cell migration and invasion of the tumor in siBECN, siATG7, or CQ-treated CAF-CM." (PMID 34575052, 2021). "As previously commented, exosomes from HD- and MM-MSCs were found distinct in terms of miRNA profile (lower content of tumor suppressor miR-15a) and higher levels of oncogenic proteins, cytokines and adhesion molecules (IL-6, CCL2, plakoglobin and fibronectin)." (PMID 34067236, 2021). "Inflammatory cytokines, such as TNF-α, IL-1β, and IL-6, are also found in tumor biopsy samples." (PMID 34194957, 2021). "Indeed, during inflammation and tumor conditions, cancer stromal fibroblasts upregulate IL-6 release, which, in turn, induces tumor angiogenesis." (PMID 33923292, 2021). "However, some reports claimed that the secretion of IL-6 from MSCs in tumor sites can promote tumor growth by its regenerative activities." (PMID 33933086, 2021). "IL-6 is a potent stimulator of STAT3 signaling in the tumor microenvironment." (PMID 34771643, 2021). "Crosstalk between tumor and hepatic cells drives fibrosis through pro-fibrogenic interleukins production (IL-6, IL-8), integrin expression, and collagen deposition, which, together, enshroud the tumor in a stiff, protective barrier that shields it from immune surveillance and clearance." (PMID 34975924, 2021). "Schematically, they can be divided into M1-macrophages with anti-tumour activity, and M2-macrophages (CD163+), which are characterized by a pro-tumour activity through the secretion of several cytokines (IL-1, IL-6, IL-10, Vascular Endothelial Growth Factor VEGF and TGF-β)." (PMID 34206956, 2021). "Interestingly, glioblastoma-derived EVs also induce an increase in the secretion of VEGF and IL-6, as well as an increase in the phagocytotic capacity of macrophages, reinforcing their tumor-supportive phenotypes." (PMID 33738282, 2021). "L-carnitine treatment decreased the IL-6 level to that of the non-tumor-bearing mice." (PMID 34724970, 2021).
tumor (continued). "The signal transducer and activator of transcription factor 3 (STAT3) signalling pathway is upregulated in TAMs and is responsible for the production of tumor-promoting inflammatory molecules, such as IL-10 and IL-6, as well as inhibition of the tumor-suppressive inflammatory molecule TNF." (PMID 33766119, 2021). "Inhibition of ERK5 activity or depletion of ERK5 prevented IL-6 production in tumor cells, which could be exploited for enhancing antitumor immune responses." (PMID 34671021, 2021). "IL-6 promotes NPC migration of bystander tumor cells by IL-6R/JAK/STAT3 pathway." (PMID 34165442, 2021). "Moreover, the ability of IL-6 blockade to overcome anti-PD-L1 resistance has been demonstrated in an HCC tumor model." (PMID 34298873, 2021). "However, the expression of IL6 in primary tumor tissues and BM metastases and its relationship with the disease feature of NB patients have not been fully elucidated." (PMID 34790130, 2021). "Th2 cytokines such as IL-4, IL-10, IL-5, IL-9, and IL-6 can down-regulate tumor-specific immunity." (PMID 34222249, 2021). "One study showed that CTRP4 promotes tumor survival through upregulation of IL-6 and TNF-alpha." (PMID 34906149, 2021). "IL-6 alleviates the induction of autophagy during tumor progression." (PMID 34575052, 2021). "Rather than acting directly on tumor cells, IL-6 deficiency appears to alter the bone marrow stroma to broadly create a permissive immune microenvironment." (PMID 34711820, 2021). "These evidences seem to indicate that elevated IL-6, IL-8 and IL-10 in non-tumor patients are common results of infections (including infections of different sites and different microorganisms), so our data does not support bacterial infections in the lungs The specificity." (PMID 34925324, 2021). "It was suggested that tumor CM-induced resistance in HMVECs was caused by the IL-6 autocrine loop and not by tumor derived-IL-6." (PMID 34226586, 2021). "In addition, intraoperative measurement of catecholamines and cytokines indicated that IL-6 was produced by the tumor." (PMID 34117557, 2021). "In addition, the bidirectional relationship between IL-6 with COX-2/PGE2 overexpression would perpetuate inflammatory events in tumor cells." (PMID 34178680, 2021). "IL-6 has been shown to recruit MDSCs and M2 macrophages to the TME, which indicates that targeting IL-6 would reduce immune suppression through decreasing PD-L1 levels as well as preventing tumour-induced assistance from the immune system through MDSCs and M2 macrophages." (PMID 34063096, 2021). "Moreover, MK2-mediated increase in TNF-α, IL-6, and IL1β promotes AOM/DSS-induced colitis-associated CRC and tumor growth in a syngeneic CRC xenograft model." (PMID 33922633, 2021). "At the same time, inhibition of miR-216a-5p or IL-6 induced cells after tumor cell stemness transformation is promoted, and the effect of LNT is reversed, indicating that LNT is involved in cell stemming by regulating miR-216a-5p targeting and mediating the JAK2/STAT3 signaling pathway." (PMID 34900727, 2021). "TME cells may release growth factors and cytokines such as WNT, epidermal growth factor, TNF, IL-17, and IL-6 in response to therapy-induced tumour cell death, which promotes the survival of residual tumour cells and leads to treatment resistance." (PMID 35003085, 2021). "According to the studies present in the literature, our data supported the key role of tumor-SEVs in IL-6 production; in addition, in this study, we correlated the EV-mediated increase in PD-L1 in M0 macrophages to IL-6 release and STAT3 signaling pathway activation." (PMID 34829995, 2021).
tumor (continued). "These inflammatory CAFs release factors, such as TGFβ-1, C-X-C motif chemokine ligand 12 (CXCL12), PDGF and IL-6, that enhanced tumor cell dispersion, scattering, and migration, by stimulating the chemokine receptors CCR2, CCR5, and CXCR1/2 and Ras-activating receptors, expressed by BC cells." (PMID 34885027, 2021). "However, blockade of AhR directly suppressed the IL-6 secretion and tumor development induced by TDO2." (PMID 34657635, 2021). "IL-6 is understood to modulate the tumor microenvironment significantly." (PMID 34681685, 2021). "Additionally, immunostaining for IL-6 demonstrated significant upregulation of IL-6 in irradiated IGFBP3-expressing tumor cells (n = 5; IRS: 4.6 ± 0.8718 per section) relative to controls (n = 5; IRS: 7.6 ± 0.4 per section; p = 0.0143)." (PMID 33712045, 2021). "Furthermore, we found higher levels of IL6, pSTAT3 and pERK1/2 in tumor tissues in the IMR32 and BMSC co-injection group, which was significantly decreased upon LPC stimulation." (PMID 34790130, 2021). "The relevance for the upregulation of Fam20c in the tumor of PD-1cKO mice is unclear and may be related to the phosphorylation of cytokines such IL-6, a known a substrate of Fam20c." (PMID 34912335, 2021). "IL-6 in the tumor microenvironment are an important determinant of alternative macrophage activation and could induce macrophage M2 polarization, and M2 macrophages can produce MMP12." (PMID 34863141, 2021). "Similarly, IL-6 and IL-32 participate in the immunosuppressive regulation of the tumor microenvironment." (PMID 34349753, 2021). "Analysis of IL1RA showed close correlation between CART expansion and IL1RA secretion, suggesting that CART cells could efficiently synthesize IL1RA and anti-IL6 scFv while eradicating the tumor cells." (PMID 33907185, 2021). "Indeed, hemolytic RBCs triggered TAM polarization toward a M1-like phenotype, as evident by the expression of M1 marker transcripts (Il6, Nos2, and Tnfa) and their increased anti-tumor activity." (PMID 34177955, 2021). "Both tumor diameter and IL-6 values predicted DSS and recurrence." (PMID 32621022, 2021). "Pro-inflammatory cytokines (IL-6, IL-8, TNF-α, soluble interleukin-2 receptor (sIL-2R)) are key-molecules involved in the crosstalk between stromal and cancer cells, their expression being, to some extent, associated with tumor growth promotion or inhibition." (PMID 34202728, 2021). "Moreover, the deletion of IL‐6 in these mice reduced the incidence of tumours and metastatic frequency." (PMID 34779563, 2021). "In addition, mast cells release VEGF, platelet-derived growth factor-β (PDGF-β) and IL-6 that promote angiogenesis, allowing for enhanced blood vessel formation, cellular proliferation and tumor growth." (PMID 34063789, 2021). "During high intensity and long-duration exercise, there is an acute up-regulation of IL-6 release, which might increase the infiltration of natural killer cells in cancer tissue and thereby decrease tumor growth, as has been shown in rodents." (PMID 33801684, 2021). "ELISA, protein microarrays and quantitative Polymerase Chain Reaction (qPCR) were used to investigate whether tumor could up-regulate IL-6." (PMID 34863141, 2021). "Furthermore, IL-6 secreted by tumor ECs is responsible for the generation of a small sub-population of CSCs in head and neck squamous cell carcinomas." (PMID 34073394, 2021). "Additionally, all coordination compounds, with emphasis on derivatives 1 and 8, reduced the secretion of IL-6 by tumor cell lines." (PMID 34768844, 2021). "IL-6 mediated STAT3 activation in the tumor microenvironment inhibits functional maturation of DC to activate effector T-lymphocytes, blocking the anticancer immunity leading to a therapeutic blockade of the IL-6 complex." (PMID 33708198, 2021). "IL-6 directly stimulates the expression of STAT3 downstream targets in tumor cells." (PMID 35155571, 2021).
tumor (continued). "To interrogate if SCEL overexpression in tumor cells can influence adjacent stromal cells that alter TME favorable for tumor progression, we used a liquid suspension array method and found that IL-6, IL-8, IL10, and MIP-1a were markedly downregulated when SCEL was knocked down in GBC-SD." (PMID 33414368, 2021). "Moreover, it has been also shown that luteolin is able to neutralize IL-6 downstream effects in keratinocytes as well in a wide casuistry of tumour cell lines." (PMID 33525692, 2021). "Furthermore, LyeTx I-b seems to be an efficient regulator of the 4T1 tumor microenvironment by modulating several cytokines, such as TGF-β, TNF-α, IL-1β, IL-6, and IL-10, in primary tumor and lung, spleen, and brain." (PMID 34572719, 2021). "In addition, tumor stroma-derived IL-6 has been shown to promote tumor angiogenesis and tumor-stroma interaction." (PMID 32940862, 2021). "In addition, tumor cell-derived TGF-β suppresses IL-6 expression in adjacent fibroblasts which in turn, inhibits NF-κB signaling." (PMID 34858425, 2021). "Importantly, PI3K-driven cancer activates the NF-κB-dependent transcriptional profile, increasing expression and secretion of cytokines and chemokines, especially IL-6, which helps to generate a pro-tumor microenvironment and facilitate tumor progression." (PMID 34356110, 2021). "This suggests that IL-6 secreted by TAMs may affect tumor proliferation, migration and adhesion through up-regulated IL-6R." (PMID 34717710, 2021). "Further, quercetin inhibited tumor promotion by downregulating the pro-inflammatory cytokines IL-6 and IL-10; pro-survival molecules downstream of PI3K/AKT/mTOR, Wnt/β-catenin, and STAT3 such as c-FLIPL; and molecules linked to cell proliferation, including cyclin D1 and cMyc." (PMID 34950252, 2021). "Furthermore, IL‐6 levels are correlated with tumor size, stage, and metastasis in patients with CRC." (PMID 34131122, 2021). "Of note, Il6, which can promote tumor progression, was significantly downregulated." (PMID 34887423, 2021). "The activation of the IL-6/JAK/STAT3 signaling pathway can inhibit the function of immune cells in the tumor microenvironment, and inhibition of the IL-6/JAK/STAT3 signaling pathway can inhibit the growth of tumor cells and alleviate the immunosuppression in the tumor microenvironment." (PMID 34422050, 2021). "In this regard, we have detected inflammatory factors including IL-1, IL-6, and TNF-α to help identify whether the increase of IL-5 and IFN-γ levels was caused by tumor progression or the concurrent inflammatory conditions." (PMID 34239620, 2021). "The results of GSEA show that terms associated with multiple tumor hallmarks, such as apoptosis, epithelial-mesenchymal transition, inflammatory response, TNFA signaling, and IL6-JAK-STAT3 signaling, were predominantly enriched in cluster 2 (NOM p and FDR q-value < 0.001)." (PMID 34802433, 2021). "A continuous increased expression of SATB1 has been described to convert inflammatory anti-tumor DCs into pro-tumor DCs by enhanced secretion of pro-tumorigenic cytokine IL-6 and immunosuppressive factor Galectin-1, activating immune-evasive pathways in these cells." (PMID 33761971, 2021). "IL-1β and IL-6 participate in inducing IL-8 expression in polymorphonuclear leukocytes (PMNs), which in turn enable the extravasation of MCs.TANs are neutrophils engaged at tumor site and can be anti-or pro-tumor phenotypes, N1-TANs and N2-TANs, respectively." (PMID 35011682, 2021). "IL-6 is a type of cytokine with various of biology activity and secreted from T lymphocytes, fibroblasts, mononuclear macrophages, etc. when inflammation, necrosis, and neoplasm occur." (PMID 33411151, 2021). "Furthermore, IL‐6 can exert an impact on other cells within the TME to maintain a favorable growth ambience of tumor cells for the ease of angiogenesis and tumor evasion from immune surveillance." (PMID 34459122, 2021).
tumor (continued). "In addition, in comparison to the in vivo findings, in vitro experiments testing the combination of IL-6 and anti-PD-1 further revealed that inhibiting IL-6 reverses anti-PD1-induced tumor cell aggressiveness to some extent." (PMID 33707313, 2021). "We then tested whether hypoxia-induced IL1A and IL6 expression in tumor cells and macrophages when co-cultured together." (PMID 34362882, 2021). "IL-6 trans-signaling represents the circulating complex IL-6/IL-6Rα binding to the ubiquitous membrane gp130 signal transducer, and it has been shown to contribute to anti-tumor adaptive immunity by guiding lymphocyte trafficking to lymph nodes and tumors." (PMID 33708198, 2021). "IL-6 can recruit ADSCs in the tumor site and induce the EMT in the cancerous cells." (PMID 34440886, 2021). "SMAD4 plays a critical role in tumor progression and induces proinflammatory cytokines, such as interleukin (IL)-5, IL-6, and IL-13, which might induce a tumor-promoting microenvironment." (PMID 33802174, 2021). "Having said all that, IL-6 seems to fit very well to the concept of the tumor microenvironment." (PMID 34681685, 2021). "However, blocking IL-6 signals by anti-IL-6R antibody therapy was sufficient to suppress tumor formation in anti-IL6-R-treated Apcmin/+Ripk3-/- mice." (PMID 33996591, 2021). "IL-6 directly acted on tumor cells and induced the increasing expression of STAT3 target genes." (PMID 34712264, 2021). "Moreover, the increased expression of CRYBB2 in TNBC cell lines enhanced cell proliferation, tumor growth, interleukin 6 (IL6) production and expression of a panel of genes associated with EMT and metastasis." (PMID 34071280, 2021). "Tumor-associated fibroblasts (TAFs) mediated monocytes’ migration into tumor sites by secreting CXCL12 and induced their transformation into CD14+HLA-DR-/low MDSCs by IL-6 mediated STAT3 activation." (PMID 34680276, 2021). "IL-6 mediates its activity through IL-6R expressed on tumour cells and GAMs." (PMID 33803414, 2021). "Thus, reversal of Bev-mediated suppression of angiogenesis by IL-6 signal blockade was maintained in the presence of tumor cells." (PMID 33833265, 2021). "STAT3-enhanced activation in CRC occurs from IL-6 in the serum and the tumor microenvironment, from growth factors and growth factor receptors, tyrosine kinases (Src, Bcr-Abl), and loss-of-function mutations for the STAT3 suppressors/inhibitors (phosphatases, SOCS, PIAS)." (PMID 34440220, 2021). "In addition, this long term chemotherapy can also enhance proliferation of cancer stem cells (CSCs) that secrete more than 100 times more IL-6 than parent cells, which induces up-regulation of NF-κB to support anti-apoptosis, reducing anti-tumor efficacy." (PMID 34669701, 2021). "Proinflammatory and profibrotic cytokines such as transforming growth factor β, interleukin 6, platelet-derived growth factor, and matrix metalloproteinases may affect the radiation response and tumor recurrence." (PMID 34407855, 2021). "In addition, IL-6 produced by BM-derived suppressor cells, Dendritic cells and CAFs can also participate in the formation of tumor-promoting immunosuppression network." (PMID 34790130, 2021). "Tumor-derived exosomal miR-1247-3p triggers the activation of fibroblast by fueling NF-κB signaling consequently stimulates the CAF to secrete a greater abundance of IL6 and IL8, instigating the cancer cells to an EMT phenotype with enhanced lung metastases." (PMID 34760886, 2021). "In cancers, studies have reported that tumor-derived factors such as granulocyte-macrophage colony-stimulating factor (GM-CSF), interleukin 6 (IL-6), long non-coding RNA HOXA transcript at the distal tip (HOTTIP) and high-mobility group box-1 (HMGB1) can induce PD-L1 expression on neutrophils." (PMID 34519637, 2021). "Elevated IL-8 and IL-6 mRNA levels enhance tumor cell proliferation." (PMID 34093809, 2021).